INS (insulin)
Diseases named in the same sentence as INS in open-access papers (continued):
Sharing a sentence is not in itself a finding about the gene and the disease.
Obesity (continued). "In turn, disruption of insulin signaling may be one of the causes of atherogenic dyslipidemia in aging and obesity." (PMID 38068822, 2023). "In addition, miRNAs regulate many biological processes associated with obesity, including adipogenesis, insulin secretion, and glucose uptake." (PMID 36873932, 2023). "Inflammation caused by obesity leads to alterations in insulin signalling pathways." (PMID 38132872, 2023). "Moreover, MCP-1 expression in the visceral adipose tissue decreases the insulin-stimulated glucose uptake, thus contributing to pathological conditions associated with obesity, such as hyperinsulinemia and type 2 diabetes mellitus." (PMID 36670674, 2023). "This profile is associated with a deteriorated insulin response and obesity." (PMID 38327649, 2023). "It has been proposed that short-term exposure of β-cells to free fatty acids (FFA) increases glucose-stimulated insulin secretion, while obesity-associated chronic exposure to high FFA levels promotes β-cell hypertrophy and insulin hypersecretion, ultimately causing β-cell dysfunction and death." (PMID 37274331, 2023). "In addition, a study of postmenopausal women indicated that obesity and androgens were independently associated with insulin sensitivity." (PMID 36767197, 2023). "In some cases, insulin infusions during COVID-19 was linked to cytokine storm in obesity." (PMID 36992811, 2023). "Likewise, PKCδ inhibited insulin signaling and increased glucose uptake in a mice model of obesity due to leptin receptor mutation." (PMID 37611829, 2023). "Future studies evaluating the relationship between glucose and insulin tolerance with neuronal loss in Lepob/ob and LepRNull/Null mice will be important to determine the contribution of these variables to changes in brain cellular composition in obesity." (PMID 37013172, 2023). "Nowadays, oxidative stress is well-recognized to be closely associated with the onset and progression of several obesity-related complications within the framework of a complex crosstalk involving other intertwined pathogenic events, such as inflammation, insulin disturbances, and dyslipidemia." (PMID 37672200, 2023). "Cytosolic nucleic acid sensing has been recently shown to stimulate thermogenic adipocyte differentiation and protect from obesity; however, DNA efflux from adipocyte mitochondria is a potential proinflammatory signal that causes adipose tissue dysfunction and insulin resistance." (PMID 37830559, 2023). "In conclusion, we used Mendelian randomization to determine the effects of T2DM, fasting insulin, and HbA1c on the three testosterone levels after controlling for SNPs associated with obesity and BMI and adjusting for confounding factors such as BMI, TG, LDL, and serum adiponectin." (PMID 37900148, 2023). "After adjustments, overweight/obesity was associated with age, family history of overweight/obesity, total daily insulin dose, hypertension, adherence to diet, type of health care insurance, use of metformin, levels of C-reactive protein, triglycerides, uric acid and HDL-cholesterol." (PMID 36823646, 2023). "Adipose tissues secreting a number of adipokines regulate insulin sensitivity, energy metabolism, and vascular homeostasis, so the dysfunction of the adipose tissue is linked with the incidence of obesity accompanied with insulin resistance, hypertension, and cardiovascular disease." (PMID 37822716, 2023). "Furthermore, NGF is also positively associated with salivary insulin, blood pressure, obesity, and anthropometric measures." (PMID 38202116, 2023). "Another RCT among 15 youth with obesity demonstrated increases in total adiponectin with reductions in IL-6 following a lifestyle intervention that did not induce weight loss but significantly reduced fat mass and improved insulin sensitivity." (PMID 37299403, 2023).
Obesity (continued). "In this context, VLCKD may represent a preventive measure in postmenopausal women with obesity, to reduce visceral adipose tissue, inflammatory status, growth factors such as insulin and IGF-1, and to reduce the risk of endometrial cancer." (PMID 37405618, 2023). "Indeed, adiponectin analogs are now considered one of the promising new therapeutic targets for obesity-linked hyperglycemia, that mitigates obesity and improves insulin sensitivity." (PMID 36200436, 2023). "Moreover, a decrease in growth hormone secretion has been associated with obesity and the suppression of insulin secretion led to weight and fat mass reduction." (PMID 37620670, 2023). "DM is a markedly heterogeneous disease, and an emerging paradigm in the non-oncology population is the identification of groups or clusters of individuals with phenotypically distinct DM (e.g., insulin-resistant, insulin-deficient, age-related, and obesity-related)." (PMID 37675136, 2023). "Considering the obesity paradox, we investigated whether MetS and non-insulin-based IR indices can predict all-cause mortality and renal outcome in patients with stage 1–4 CKD." (PMID 37255931, 2023). "Furthermore, this cytokine has been associated with reduced insulin sensitivity and decreased levels of anti-inflammatory cytokines in visceral fat obesity." (PMID 37755259, 2023). "Similarly, vitamin D appears to improve insulin sensitivity through various mechanisms, and recent studies have found a strong link between vitamin D deficiency, obesity, and metabolic syndrome." (PMID 38068801, 2023). "Indeed, higher osteocalcin levels were reported to be associated with greater insulin sensitivity, lower BMI and lower systolic blood pressure, while T2M and obesity were associated with lower osteocalcin concentrations." (PMID 37755271, 2023). "Higher visceral fat might enter and accumulate in the liver via the portal system, which increases liver TG levels, reduces insulin reabsorption, causes metabolic disturbances, and increases the risk of IR, thus finally leads to obesity." (PMID 37715242, 2023). "Moreover, acetate has been found to positively influence appetite, insulin and ghrelin release, and obesity and its associated complications by influencing the parasympathetic neural system." (PMID 36992691, 2023). "Thus, pathways associated with PERK significantly influence insulin sensitivity and β cell function, playing a crucial role in diabetes research and obesity." (PMID 38140341, 2023). "Moreover, obesity is associated with insulin-induced reductions of sex hormone-binding globulin (SHBG), which increases the bioavailability of sex steroids including estradiol." (PMID 38027308, 2023). "We hypothesize that different OGTT patterns of glycemia in pregnancies complicated by obesity are associated with distinct clinical and biochemical characteristics, determined by impairments of insulin secretion or insulin sensitivity." (PMID 36950879, 2023). "Although it is well known that obesity causes insulin resistance of skeletal muscle, it remains unclear whether Rac1-mediated signaling is indeed impaired in insulin-resistant states associated with obesity." (PMID 37511290, 2023). "Thus, the increase in white adipose tissue (WAT) inflammation during obesity has been associated with impaired insulin signaling, glucose intolerance, and changes in glucose and fatty acid metabolism." (PMID 37179836, 2023). "However, obesity can cause chronic hyperinsulinemia and/or resistance to peripheral insulin, inducing hypoinsulinemia in the brain, with consequent reduction of the glutamate receptor." (PMID 36767806, 2023). "Increasing evidence suggests that skeletal muscles may play a role in the pathogenesis of obesity and associated conditions due to their impact on insulin resistance and systemic inflammation." (PMID 37374197, 2023). "In summary, changes in hepatic DG might be associated with the anti-obesity and insulin-sensitizing effects of 1,25(OH)2D3." (PMID 37124226, 2023).
Obesity (continued). "Insulin-deficient diabetes might be associated with lower risk of cardiovascular disease compared to insulin-resistant diabetes driven by obesity." (PMID 37667316, 2023). "Additionally, vitamin D3 has been reported to be crucial in reducing the risk of metabolic syndrome, including obesity, enhancing glucose uptake and improving insulin sensitization." (PMID 37764823, 2023). "A popular hypothesis is that added sugars and high glycaemic carbohydrates may cause obesity by excessive stimulation of insulin, which not only stimulates the storage of fat but also blocks lipolysis in the adipocyte." (PMID 37482773, 2023). "While the rise in wound healing may be attributed to systemic causes because of increased insulin sensitivity and obesity, DNMT1 targeting was recognised as a viable treatment technique in diabetic macrophages and needs more investigation." (PMID 36831151, 2023). "However, insulin hypersecretion by the pancreas has been implicated in obesity development and pathogenesis." (PMID 36829976, 2023). "Individuals with overweight or obesity, defined as body mass index (BMI) ≥25 and ≥30 kg⋅m2, respectively, are at higher risk of impaired metabolic homeostasis, reduced insulin sensitivity and postprandial lipid metabolism, which can be contributed by physical inactivity." (PMID 37123278, 2023). "Thus, this review aims to examine the mechanisms of amino acid catabolism and to support the idea that this process is associated with the immune response, abnormalities during obesity, in particular insulin resistance, and the regulation of thermogenesis." (PMID 37571315, 2023). "The mechanism whereby maternal obesity influences preeclampsia is unknown, although obesity-related inflammation, oxidative stress, insulin resistance, and underlying hypertension have been suggested." (PMID 36768469, 2023). "However, there is a recent tendency towards identifying their involvement in the pathogenic mechanisms of obesity, such as fat accumulation, insulin dysfunction and impaired lipid and glucose metabolism." (PMID 37104004, 2023). "Furthermore, low-fat diets have not been shown to lead to weight loss necessarily, and novel models such as the Carbohydrate-Insulin Model (CIM) of obesity are growing in popularity." (PMID 37063330, 2023). "Moreover, IL-10 overexpression increases insulin sensitivity, protects skeletal muscle from obesity-associated macrophage infiltration and decreases production of inflammatory cytokines." (PMID 36994095, 2023). "In T2DM, the most common form and often associated with obesity and a sedentary lifestyle, multifactorial causes (such as genetic and environmental factors) induce resistance to insulin action, and the pancreas is unable to produce enough insulin to balance this resistance." (PMID 37047748, 2023). "Surprisingly, selecting for low physical activity almost exclusively affected the brains of female LVR as the male LVR appear to be spared from most cognitive deficits relative to within sex controls, despite the presence of systemic risk factors like insulin resistance and obesity." (PMID 37077501, 2023). "It remains unclear if increases in BCAA and/or BCKAs are a consequence or cause (or both) of IR in adolescents; indeed, high levels of BCAA might serve an adaptive function, increasing insulin secretion as a response to obesity‐associated IR." (PMID 36415168, 2023). "It has been suggested that disruption of the biological clock associated with night work may lead to obesity, impaired insulin secretion, and abnormal glucose homeostasis." (PMID 37904784, 2023). "In the setting of obesity and advancing age, microglia activation is commonly observed in the hypothalamus, which has been linked to neuronal endoplasmic reticulum stress, declines in insulin and leptin sensitivity, and faster aging in male and female mice." (PMID 37425648, 2023).
Obesity (continued). "Furthermore, in obesity and IR, M1 macrophages polarize and secrete inflammatory cytokines, causing reduced cardiac insulin signaling and promoting DCM development." (PMID 37152931, 2023). "Additionally, studies on patients with obesity have demonstrated that a high protein intake during weight loss impairs insulin signaling in muscles and normal glucose uptake rates." (PMID 36776765, 2023). "The mechanisms governing the PC-mediated association between obesity and T2D could be via fatty acid (FA) and insulin signaling pathways." (PMID 36837846, 2023). "Interestingly, the maternal intake of micro- and macronutrients during the pregnancy can also influence the offspring’s risk of obesity, IR, and impaired insulin secretion through epigenetic mechanisms." (PMID 36980074, 2023). "In line with this hypothesis, Danai and collaborators showed that inducible deletions of Map4k4 cause obesity and insulin sensitivity in KO mice." (PMID 36469137, 2023). "However, a systematic review and meta-analysis of 28 studies highlighted that the diagnosis of PCOS independently of obesity was associated with a 27% decrease in insulin sensitivity." (PMID 37630842, 2023). "Obesity mediates the development of other obesity-related complications, such as T2D, hypertension, obstructive sleep apnea syndrome, and male hypogonadism, by decreasing sensitivity to insulin and causing IR." (PMID 37537674, 2023). "However, recent studies reported that metabolically unhealthy obesity (MUO) exerts a higher risk of developing T2DM than metabolically healthy obesity (MHO) because of its higher state of insulin resistance." (PMID 36701395, 2023). "Importantly, Cdc42 plays a vital role in cellular processes associated with the insulin and leptin signaling pathways, which are integral elements involved in obesity development if misregulated." (PMID 38068822, 2023). "Because of the great number of children and adolescents having or at risk of having obesity and because IR may occur as part of the physiological changes in puberty, early detection of impaired insulin sensitivity in pubertal children is pivotal." (PMID 36843603, 2023). "In particular, arginine and proline metabolism could be associated with obesity, resistance to insulin, and lipid levels." (PMID 37048225, 2023). "In addition, they presented higher rates of elevated 1-hour plasma glucose that has been associated with lower insulin sensitivity and early insulin secretion in children and adolescents with obesity." (PMID 36670156, 2023). "Moreover, obesity and associated metabolic dysfunctions such as impaired glucose and insulin sensitivity are correlated with impaired PI3K-AKT pathway, a TRKB downstream target." (PMID 37956053, 2023). "In conclusion, as a functional food, quinoa may be useful in the prevention of obesity and associated metabolic outcomes such as glucose intolerance, disrupted pancreatic β‐cell function, hepatic insulin resistance, and lipid accumulation." (PMID 37970433, 2023). "An animal experiment concluded that plasma citrulline and ornithine levels were elevated in obese and insulin-deficient mice, and further suggested that citrulline could be an early indicator of obesity-dependent metabolic impairment." (PMID 36936143, 2023). "In-depth characterization of people with overweight or obesity has demonstrated that microbial gene richness is negatively associated with various metabolic parameters, including fat mass, leptin levels, fasting insulin, HOMA-IR, systemic inflammation, and TAG levels." (PMID 37581871, 2023). "Both vaspin mRNA and serum levels are associated with obesity and impaired insulin sensitivity." (PMID 36979443, 2023). "Obesity may cause IR, which occurs as a bodily response to chronic hyperinsulinemia and the interference of inflammatory mediators with downstream insulin signaling molecules." (PMID 37237974, 2023). "Insulin hypersecretion in these models is linked to lipid excess in obesity." (PMID 36917141, 2023).
Obesity (continued). "The dysregulation of gut hormones present in obesity is implicated in excessive nutrient intake, impaired insulin signaling leading to hyperinsulinemia and T2DM and chronic low-grade inflammation arising from adipose tissue, which are all mechanisms involved in the development of cancer." (PMID 37686769, 2023). "In the context of clinical data, a study using ten 28 h “day” shift-work paradigm in humans reported dysregulated plasma leptin, insulin, glucose, and cortisol concentrations and observational studies support the increased risk of obesity associated with night shift workers." (PMID 36834801, 2023). "In addition, due to its mechanism of action, it alleviated insulin and leptin resistance caused by obesity." (PMID 37510734, 2023). "The roles of minerals in obesity received increasing attention recently due to its oxidant or antioxidant functions and effects on insulin and glucose metabolism that may be associated with obesity." (PMID 38150411, 2023). "Furthermore, key risk factors for NAFLD, including insulin insensitivity, obesity, and dyslipidemia, are alleviated by FGF-21, and FGF-21 has been reported to reverse liver steatosis while counteracting obesity and enhancing insulin sensitivity." (PMID 38222178, 2023). "This has been shown with metformin therapy in low-birthweight girls, and with weight loss in adults/adolescents with PCOS and obesity, with reduced adiposity and insulin sensitizing addressing hyperandrogenism, insulin resistance and restoring normal ovulatory function." (PMID 37015099, 2023). "ANKO mice display an increased VAT PPARg (peroxisome proliferator-activated receptor gamma) Ser273 phosphorylation, a post-translation modification that impairs its insulin-sensitizing effects and modulated expression of most of its obesity-linked targets at the mRNA level." (PMID 37761000, 2023). "Moreover, tadalafil improves insulin action on muscle glucose uptake by prolonging NO/cGMP signaling in women with obesity-linked IR." (PMID 35449082, 2022). "However, in the main, telomeres appear to be shorter in patients with obesity, perhaps partially due to the influence of insulin, and shorter telomeres predispose cells to ‘Genome instability and mutation’." (PMID 36038791, 2022). "Indeed, pathway analysis showed that genetic susceptibility to obesity can involve “insulin secretion/action, energy metabolism, lipid biology and adipogenesis”." (PMID 35896818, 2022). "First, IFN-α, IFN-β, IFN-γ, and IFN-λ1 were associated with obesity and insulin sensitivity." (PMID 36552805, 2022). "In addition, the knock-out of the Klotho gene in leptin-deficient mice reduces obesity and increases insulin sensitivity." (PMID 35053218, 2022). "The divergence between the disappearance of metabolic improvement despite reduced body weight might be caused by the age-related decline of insulin sensitivity in obesity." (PMID 35897098, 2022). "Hence, it is no surprise that common risk factors such as a sedentary lifestyle and obesity are correlated with decreased muscle contraction, impaired energy metabolism, and insulin resistance." (PMID 35563026, 2022). "Overall, 13 were associated with maternal obesity, insulin sensitivity and GDM." (PMID 35885031, 2022). "Hence, maternal SCFA levels influence embryonic insulin levels and embryonic gut satiety hormone secretion, potentially modulating the offspring’s risk for later development of obesity." (PMID 35464026, 2022). "We tested the hypothesis that adipose tissue dysfunction is exaggerated in T2D compared with obesity alone and if this is linked to the mechanisms of insulin resistance in skeletal muscle." (PMID 35805088, 2022). "Furthermore, consistent with this, it has been reported that low expression of the SNARE proteins STX1, SNAP25, and VAMP2 is associated with insulin secretory defects in rodents and humans with obesity and type 2 diabetes." (PMID 35804190, 2022).